SNORD121B (small nucleolar RNA, C/D box 121B)
Gene: Small nucleolar RNA gene on chromosome 9 (33,934,296 to 33,934,376, reverse strand). Ensembl gene ENSG00000238300.
Gene Ontology:
Biological process: RNA processing
Cellular component: nucleolus
Homologues: Orthologues: chimpanzee SNORD121B (100% identical), macaque SNORD121B (99% identical), dog SNORD121B (93% identical), pig SNORD121B (86% identical), mouse Gm22888 (78% identical), rabbit SNORD121B (78% identical), rat Snord121b (72% identical). Paralogues in human: SNORD121A (67% identical).